CCL2 (C-C motif chemokine ligand 2)
Diseases named in the same sentence as CCL2 in open-access papers (continued):
Sharing a sentence is not in itself a finding about the gene and the disease.
tumor (continued). "Our studies showed that PLX3397 dramatically depleted macrophages in the tumor microenvironment and PLX4032 slightly decreased the number of macrophages, likely due to down-regulation of secreted cytokines such as CCL2 that could recruit immunosuppressive cells." (PMID 25939769, 2015). "Since the tumor cells have already metastasized and escaped the primary tumor microenvironment, CCL2 may no longer be necessary." (PMID 26327448, 2015). "Particularly, ANGPT2 and CCL2 were specifically released by the sMSCs leading to the much more aggressive tumor growth, although no superior production of other potent angiogenic molecules like VEGFs was seen in the sMSCs compared to other MSCs (unpublished data)." (PMID 25883937, 2015). "Moreover, a similar pattern (AR increased, CCL2 significantly decreased) is observed in metastases from patients who did not receive ADT, supporting the idea that CCL2 is only required at the primary tumor site." (PMID 26327448, 2015). "Furthermore, other factors released by tumor stroma components like IL-8, GRO, IL-6, or CCL-2 could also be involved in MSC recruitment to HCC." (PMID 25147818, 2014). "Therefore downregulated expression of CCL2 and VEGFA following AhR knockdown may decrease the blood supply necessary for tumor growth." (PMID 24932473, 2014). "Resistance to therapy is due to multiple factors which include both tumor cell alterations during tumor development and progression, and extrinsic factors present in the microenvironment, including chemokines such as Chemokine (C-C motif) ligand 2 (CCL2)/monocyte chemotactic protein-1." (PMID 24980831, 2014). "As CCL2 is a chemotactive factor for monocytes and could be integral in the recruitment of macrophages to the site of tumors development, we tested whether ablation of CCL2/CCR2 signaling affected tumor growth in a syngeneic transplant model." (PMID 25505466, 2014). "Collectively, published results and the data from our studies suggest that CCL2 may or may not exert tumor growth-promoting effects depending on the host environment." (PMID 23967166, 2013). "However, research into CCL2-mediated infiltration has mainly focused on the role of tumor-infiltrated macrophages but not other cell types." (PMID 22319587, 2012). "Furthermore, α-TEA treatment modulated the tumor microenvironment in a proinflammatory fashion, as we found significantly higher IL-6 and CCL5 levels and a trend toward higher levels of other proinflammatory mediators (IL-1β, CCL2, CCL3, CCL4)." (PMID 21232138, 2011). "However the ability of CCL2, CXCL1, CXCL5 and VEGF to significantly reduce IL-12p70 production by DCs is important, as this may potentially result in a reduced anti-tumour Th1 response in vivo." (PMID 22125641, 2011). "In addition to their ability to promote the release of CCL2 and CCL5 by the tumor cells, it is possible that TNFα and IL-1β act directly to elevate processes that are required for local recurrence or metastasis formation, which identify the IDC-with-relapse group of patients." (PMID 21486440, 2011). "No CCL2 expression was detected in the stroma of any of the tumours." (PMID 15900302, 2005). "In addition, the IT L1 peptide/polyI:C-treated mice displayed an increase in CXCL10, CCL2, CCL3 and CCL4 and GM-CSF in the tumor lysate which could be involved in the recruitment, retention and maturation of myeloid and lymphoid cells in the tumor." (PMID 40280970, 2025). "Given our findings that rs13900 modulates HuR binding and thereby influences CCL2 expression, targeting HuR-ARE interactions could offer a promising therapeutic avenue for conditions involving heightened monocyte/macrophage recruitment, such as inflammatory, cardiovascular, and neoplastic diseases." (PMID 37961304, 2025).
tumor (continued). "Furthermore, a significant positive correlation between B7-H3 and CCL2 levels has been observed; targeting B7-H3 resulted in decreased M2 macrophage populations as well as inhibited their recruitment through the downregulation of CXCL1 and CCL2 within the tumor microenvironment (TME)." (PMID 40801642, 2025). "Additionally, SOX9‐AS1 might influence the secretion of chemokines such as CCL2 and CXCL12, which recruit immunosuppressive cells like regulatory T cells (Tregs) and myeloid‐derived suppressor cells (MDSCs), further inhibiting anti‐tumour immune responses." (PMID 39550706, 2024). "Additionally, CCL2 preferentially binds to CCR2 receptors and initiates a variety of signal transduction pathways (including more classical M1/M2 activation pathways, such as the PI3K/AKT, ERK, JAK-STAT and NF-κB signaling pathways), stimulating cell migration and mediating tumor pathogenesis." (PMID 38769475, 2024). "Additionally, a Phase I trial of a human IgG1 monoclonal antibody, carlumab, that is specific for CCL2 in patients with solid tumors refractory to standard treatments demonstrated no objective anti-tumor response out of 44 patients (with 1 PDAC patient among the cohort)." (PMID 38339310, 2024). "During tumour progression, TAMs may be more inclined to the M2 polarized state and can secrete various growth factors such as VEGF, PDGF, EGF, chemokines and cytokines such as IL-10, TGF-β, CCL2 and CXCL12; thus, the tissue trophic function of M2-type TAMs instead promotes tumour progression." (PMID 39060648, 2024). "Furthermore, Ccl2 expression in tumor ECs isolated from EC-Gαs-KO mice was higher compared to control mice, and tumors from MMTV-PyMT mice crossed with EC-Gαs-KO animals also expressed significantly more Ccl2 compared to tumors without loss of endothelial Gαs." (PMID 36374225, 2023). "Furthermore, microvessel density, defined with anti-CD31 Ab staining, was reduced in mice treated with anti-mouse CCL2 Ab, suggesting that CCL2 produced by stromal cells, but not cancer cells, plays a critical role in tumor growth and angiogenesis during disease progression in this BC model." (PMID 37208442, 2023). "Moreover, in desmoplasia‐associated cancers, fibroblast activation protein (FAP) could up‐regulate the expression of CCL2 through STAT3 signalling pathway, which enhances the recruitment of myeloid‐derived suppressor cells and promotes proliferation of tumour matrix and leads to poor prognosis." (PMID 36872292, 2023). "Therefore, we used our orthotopic syngeneic mammary gland grafting model with engineered tumor-cell-derived TNC levels to further investigate (a) whether CCL2 impacts the behavior of macrophages resident within the tumor and (b) whether there is any functional interplay between TNC and CCL2 in vivo." (PMID 37176074, 2023). "Similarly, we hypothesized that the chemokines CCL2 and CCL5—which are pro-metastatic chemokines that promote tumor cell invasion and act mainly through the Gαi-signaling receptors CCR2 and CCR5, respectively —also contribute to increased invasion of WT-PD-L1-MDA cells." (PMID 35205789, 2022). "Interestingly, CCL2 and MHCII expression in the left hemisphere showed a reduction trend at 21D compared to the earlier phases, which could be justified by the secondary tumor mass occurrence." (PMID 36048342, 2022). "Instead, extracellular components, including LIF, CCL2, PDGFA, Hippo/YAP1, as well as, immune responses and angiogenesis, might pivotally participate in development of intratumor heterogeneity through remodeling methylome and transcriptome of tumor foci from same mGBM patients." (PMID 34987659, 2022). "However, whether CCL2 has positive or negative effects on tumor growth depends on it recruits pro-tumor or anti-tumor neutrophils/monocytes to the tumor." (PMID 33996815, 2021).
tumor (continued). "To further detect whether the alterations in the chemokine profiles were critical in USP12-mediated control of tumour growth, we overexpressed Cxcl1 combined with or without Ccl2 into mouse lung tumour cells and found that LLC cells, when overexpressing Cxcl1, grew more rapidly than control cells." (PMID 34381028, 2021). "Similarly, STAT5 and p38MAPK could not be activated in CCR2−/− tumour tissues after tumour cell injection, indicating that CCL2‐induced tumour cell migration had a close relationship with JAK2‐STAT5 and p38MAPK pathway activation." (PMID 34464477, 2021). "However, in our study, when we measured the markers of TAMs, including HIF-1α, CCL2, and PECAM1, we found that gemcitabine treatment potently activated the expression of TAM markers, while knockdown of IFI16 reversed the increase in TAMs in the tumor microenvironment." (PMID 34150748, 2021). "Likewise, when we explored the effects of IL1β-silenced tumor cells on co-cultured NCFs, we could observe that cocultured fibroblasts lost the expression of inflammatory cytokines, as IL6, LIF or CCL2, while acquired markers of myofibroblasts (ACTA2, PDPN, MYH11, or CNN1)." (PMID 34066976, 2021). "However, carlumab could not effectively block serum CCL2 levels and showed no anti-tumor activity as a single agent in metastatic CRPC in the clinical trial (NCT00992186)." (PMID 32824865, 2020). "Lack of Ccl2, Ccl5, and Cxcl10 expression in 4T1ρ0 cells posed the question of whether or not macrophage recruitment into 4T1ρ0 tumors early in their development was compromised, and if so, whether or not this affected tumor formation." (PMID 33329014, 2020). "In addition, as expected, CCL2 staining of the ICs was significantly positively correlated with the presence of different immune cells/cell markers, such as CD3 (T cells), CD8 (T cells), CD68 (macrophages), PD-L1 in TCs and ICs, and the percentage of stromal tumor-infiltrating lymphocytes (sTILs)." (PMID 32429318, 2020). "Thus, tumor progression may be directed by reciprocal interaction between stromal cells and tumor cells, by chemotactic action of MCP-1/CCL2 and SDF-1/CXCL12 and probable, effect of MSC-derived exosome, to create an appropriate environment for tumor aggressiveness." (PMID 30413179, 2018). "To evaluate changes in the tumor microenvironment induced by RT53 injection that could explain the increased number of T lymphocytes, we used real-time RT-PCR of tumor extracts to analyze the relative expression of the pro-inflammatory chemokine ligands CCL2 and CXCL10." (PMID 30080874, 2018). "However, a recent study using a B16 mouse melanoma model demonstrated that neither Ccr2 nor Ccr5 deficiency affect tumor infiltration of adoptively transferred CD8+ T cells, despite the fact that the tumor expresses high levels of CCL2 and CCL5 (ligands for CCR2 and CCR5, respectively)." (PMID 30483271, 2018). "Interestingly, the indicated difference in CCL2 protein levels was also apparent in CCR2 KO mice, showing that it is not the mere extent of tumor burden that determines CCL2 amounts but, instead, the ability of tumor cells to produce CCL2, a capacity that is impaired in the absence of TRAIL-R." (PMID 28212753, 2017). "Also, it is not clear from these studies whether CCL2 is solely responsible for the accumulation of monocytes in the tumor." (PMID 28220123, 2017). "However, addition of anti-CCL2, but not isotype matched control IgG, was able to reverse the naïve neutrophil killing of 67NR cells, indicating that CCL2 was needed for the neutrophil killing of tumor cells." (PMID 28143493, 2017). "However, CCL2 did not enhance killing of 4T1 or PyMT tumor cells by naïve or TEN." (PMID 28143493, 2017).
tumor (continued). "Thus, in the absence of host CCR2, tumor cell-derived CCL2 that is induced downstream of cancer cell-expressed TRAIL-R fails to promote the presence of alternatively activated myeloid cells in the tumor microenvironment, coincident with diminished tumor growth." (PMID 28212753, 2017). "Furthermore, it may not be necessary to eliminate CCL2 expression levels from the tumor to inhibit tumor progression." (PMID 27283985, 2016). "Importantly, in the absence of tumor cells, the production of CCL2 is negligible (3A and 3B)." (PMID 25599228, 2015). "Because E9 cells are already transformed and do not require a progression phase for tumor growth and because alveolar macrophages differ in function and response from macrophages present near subcutaneous tumors, we tested whether CCL2/CCR2 signaling was required for de novo lung tumor formation." (PMID 25505466, 2014). "Consistently, we also found more infiltrating CD68-positive macrophages in PCa as compared to benign prostate tissues and there were no age differences between these two groups, suggesting a potential positive correlation of macrophages and CCL2 expression in human PCa tissues." (PMID 23982944, 2013). "However, it seems that anti-CCL2 does not prevent the influx of TAMs; this could be due to the inability to reach an adequate dosage of anti-CCL2 in the tumour microenvironment to counteract the influx of TAMs." (PMID 22778767, 2012). "The radiotherapy-induced secretion of cytokines from tumor cells, such as CSF1, CCL2, and MCP3, promotes macrophage recruitment and activation from the irradiated tumor microenvironment to the non-irradiated tumor site." (PMID 40835598, 2025). "Unlike CCL2, the release of CCL5 by tumor cells not only promotes TAMs and MDSCs infiltration, participating in tumor metastasis,but also recruits CD8 + T cells to enhance adaptive immunity." (PMID 38528587, 2024). "Consistently, a series of chemokines, such as CCL2, CCL14, and CXCL2, as well as selectins were highly expressed in non-tumor–derived veins, whereas tumor-derived ones showed increased expression of genes related to collagen formation and ECM remodeling." (PMID 39345334, 2024). "Although Carlumab was well tolerated by patients, it only resulted in transient suppression of chemokine effects, did not block the CCL2/CCR2 pathway, and exhibit no anti-tumor effect." (PMID 37143666, 2023). "By day 37, in the NGP-Fluc mice, combination therapy demonstrated a significant decrease in tumor burden compared to the PBS control group (p < 0.01) and the anti-CCL2 antibody alone group (p < 0.01), but not compared to the etoposide alone group." (PMID 37964011, 2023). "In summary, tumor-derived TNC dominates the effect on myeloid cell polarization and tumor growth in this model, and treatment with anti-CCL2 antibodies does not markedly impact the tumor myeloid cell compartment." (PMID 37176074, 2023). "Thus, blocking CCL2 with soluble CCR2 fragment or inhibition of CCR2 with blocking antibody could decrease tumor accumulation of MDSCs in the tumor bone metastases model by injecting prostate cancer cells directly into murine tibiae, making it a potential target for anti-tumor therapy." (PMID 37006306, 2023). "CCL2 is a key regulator of TAM recruitment, differentiation and function and is produced by both tumor cells and non-tumor cells." (PMID 37865750, 2023). "In contrast, M-MDSCs have much lower CXCR2 expression and are not recruited to the tumor microenvironment by CXCR2 ligands, but instead by CCL2." (PMID 37686093, 2023). "To expand our findings of CCL2 and CCL5 regulated by lncSNHG5-ZNF281 signaling in promoting tumor metastasis, we evaluated CCL2 and CCL5 levels in tumor tissues and serum CCL2 and CCL5 of healthy donors and BC patients with or without metastasis." (PMID 36438499, 2022). "Pre-incubation with 1 μg/ml anakinra dramatically reduced the production of CXCL8 and CCL2 but not CCL5 for both UPCI-SCC90 and FaDu 3D tumour-stromal models." (PMID 35047989, 2021).
tumor (continued). "Although CCL2 expression in the entire cancer tissues was slightly increased overall compared with that of the normal tissues, CCL2 and CCL5 expression were not related to p16INK4A positive tumor cells." (PMID 33643790, 2021). "This review will separately discuss the chemotactic and non-chemotactic effects of the CCL2/CCR2 axis on monocytes/macrophages, T cells and tumor cells." (PMID 34804061, 2021). "The non-paired analysis confirmed significantly lower CCL2 and CCL8 expression in tumors compared to tumor-adjacent tissue." (PMID 34885960, 2021). "Data analysis also showed that the CCL2, which enhanced tumor migration ability via the PI3K/AKT/mTOR pathway, is originated from adipocytes, not the tumor cell." (PMID 34386431, 2021). "Then, the TANs that are distributed in the HCC stroma, but not in tumor cells or adjacent non-tumor hepatocytes recruit macrophages and Treg cells into HCC by secreting CCL2 and CCL17 to promote the HCC progression." (PMID 33224886, 2020). "We examined CCL2 levels in sera of control mice using ELISA and found that they were significantly increased in LLC tumor-bearing animals compared to non-tumor-bearing animals, confirming published reports." (PMID 32528880, 2020). "This leads to the adhesion of non-classical monocytes to vessel walls near the tumor, followed by the production of IL-6, MCP-1/CCL2 and MMP-9 by monocytes." (PMID 32466280, 2020). "There are no previous data on CCL2, CCL3 or CCL4 in PitNETs, but these chemokines are involved in tumour growth and invasion in other tumours, as well as in immune cell chemotaxis in cancer." (PMID 31703742, 2019). "Surprisingly anti-CCL2 monoclonal antibody treatment did not affect TAM recruitment but polarized TAMs to a more antitumor phenotype, where the tumor regression was CD8+ T-cell dependent in a murine NSCLC cancer model." (PMID 27886105, 2016). "In summary, CCL2 gene silencing decreases M2 macrophage recruitment in TNBC xenografts, and does not significantly affect tumor angiogenesis." (PMID 27283985, 2016). "In our studies, we show that local delivery of CCL2 siRNAs through Ca-TAT peptide complexes lead to efficient and sustained CCL2 knockdown in tumor cells, without adversely affecting viability or gene expression in surrounding normal mammary tissue." (PMID 27283985, 2016). "This is illustrated by the finding that extensively damaged tumor cells (60 μM ZnPC-ETL group) no longer secrete TNF-α and CCL2." (PMID 26307977, 2015). "Each of these chemokines was consistently expressed in all of the MCA-induced tumours tested and expression of most, namely CCL2, CCL7, CCL8, CCL12 and CX3CL1, was detectable only in the tumours and not in spleen and lymphoid tissue." (PMID 25495686, 2015). "Collectively, our results indicate that CCL2 and CCL12 neutralization alone or in combination favorably impact MPE development in mice and support that MPE control can be achieved by targeting tumor-host interactions rather than tumor cell survival." (PMID 23967166, 2013). "In parallel, we determined the expression of CCL2, CCL5, TNFα and IL-1β in normal breast epithelial duct cells that were in proximity to the tumor cells in biopsies of patients with DCIS, IDC-no-relapse and IDC-with-relapse." (PMID 21486440, 2011). "However, other CCLs, including CCL2, CCL3, CCL11, CCL26, and CCL28, did not exhibit significant changes in expression during tumor progression." (PMID 39859340, 2025). "Interestingly, CCL2 knockdown in the MDA-MB-231 model but not in the 4T1 model inhibited tumor growth." (PMID 38973385, 2024). "TNFɑ was also positively correlated with tumor burden (r = 0.6094, p = 0.0465), though not as strongly as CXCL10 or CCL2, indicating that higher serum levels of these cytokines may be associated with higher severity of disease." (PMID 39623404, 2024).